NPY (neuropeptide Y)
Diseases named in the same sentence as NPY in open-access papers (continued):
Sharing a sentence is not in itself a finding about the gene and the disease.
Anorexia (50 papers, 2010 to 2025). Lack of desire to eat (loss of appetite). "These SNPs are located in an intergenic region approximately 34 kb from the NPY gene, which influences many physiological processes, including circadian rhythms, anorexia, and weight loss." (PMID 33921837, 2021). "Rikkunshito attenuated anorexia and weight loss by upregulating hypothalamic orexigenic NPY and decreasing TRH." (PMID 32906727, 2020). "TNF-α, IL-6 and IL-1 mimic leptin signaling and suppress orexigenic ghrelin and neuropeptide (NPY) signaling, which result in weight loss and anorexia." (PMID 32906727, 2020). "Rikkunshito was demonstrated to ameliorate anorexia and weight loss by upregulating hypothalamic orexigenic neuropeptide Y (NPY) and decreasing thyrotropin-releasing hormone (TRH) in paraventricular nucleus (PVN)." (PMID 32906727, 2020). "Leptin act in the hypothalamus, where leptin inhibits neuropeptide Y (NPY) neurons and causes anorexia." (PMID 23579596, 2013). "Therefore, cancer-related anorexia caused by NPY deficiency cannot be treated only by administering NPY; instead, downstream signaling issues should also be addressed." (PMID 41373996, 2025). "One of the components influencing weight loss during immobilization stress, apparently, is the increased expression kinetics of anorexigenic (POMC and CART) and orexigenic (NPY and AgRP) peptides and, as a result, anorexia caused by a violation of the homeostatic circuit." (PMID 36558137, 2022). "It has been shown that low NPY serum levels are associated with anorexia in PD patients." (PMID 31191339, 2019). "NPY is an orexigenic peptide, and anorexia is one of the causes of weight loss." (PMID 28101970, 2017). "Decreases in NPY levels and nitric oxide activity are major causes of anorexia of aging, suggesting that NPY could play a key role in preventing anorexia of aging." (PMID 28101970, 2017). "In recent years, imbalance between gastrointestinal peptides such as acyl-ghrelin, motilin and NPY, and anorectic peptides such as pro-opiomelanocortin has been implicated as a cause of CINV and anorexia in cancer patients." (PMID 40045433, 2025). "They suggested that insulin, together with neuropeptide Y (NPY), are causative factors of LPS-induced anorexia, as insulin concentrations increased from the second hour after LPS injection." (PMID 35897684, 2022). "In LPS- or TNF-α-induced anorexia experimental models of acute inflammation, NPY expression in the hypothalamus is reduced, consistent with the observed decrease in food intake." (PMID 34899611, 2021). "The AgRP expression pattern is similar to NPY, as its mRNA expression increases but secretion decreases in both acute and chronic inflammatory anorexia models." (PMID 34899611, 2021). "Centrally, IL-1α is able to suppress appetite and to induce anorexia by increasing plasma concentrations of satiety-drivers tryptophan and serotonin, and by blocking neuropeptide Y (NPY) secretion." (PMID 33202621, 2020). "We suggest ARC N- and L-type Ca2+ channels as potential targets for activating, respectively, ghrelin-responsive, and unresponsive NPY neurons to treat anorexia." (PMID 32766273, 2020). "Pharmacological studies demonstrated that EA treatment at CV12 reduces the levels of plasma monoamine neurotransmitters 5-HT, 5-HIAA, DA, and NE; while simultaneously stimulating the expression of GHRL and NPY to alleviate cisplatin-induced anorexia in rats." (PMID 31635295, 2019). "Insulin can affect appetite by acting on hypothalamic neurons, promoting anorexia by decreasing NPY and stimulating POMC expression and through regulating ghrelin suppression." (PMID 28677623, 2017). "Our previous study demonstrated that RKT ameliorated cisplatin-induced anorexia in rats and reversed the cisplatin-induced decrease in hypothalamic NPY gene expression in the ARC." (PMID 28249026, 2017). "Combined with previous findings, these data imply that LPS-induced anorexia may derive from the concerted action of NPY and POMC." (PMID 37207231, 2023).
Anorexia (continued). "Heat stress inhibits the mRNA expression of NPY and induces anorexia." (PMID 35370775, 2022). "CRH induces anorexia in the brain by inhibiting neuropeptide Y (NPY)-stimulated food intake." (PMID 35887027, 2022). "Interestingly, mCoV-A59 reduced the mRNA expression of orexigenic neuropeptide-Y, consistent with the fact that infected mice display anorexia." (PMID 34151773, 2021). "In addition, genetic models of anorexia suggest that the disruption of NPY/AgRP signaling is partially due to axonal transport dysfunction." (PMID 34899611, 2021). "Furthermore, the administration of NPY or blocking the induced inflammatory response prevents the development of anorexia." (PMID 34899611, 2021). "The reversal of resistance to NPY by injecting a CRF receptor antagonist prior to exposure to the stressors verified that CRF signaling in the PVN may override the orexigenic effect of NPY and exacerbate anorexia in LWS chicks." (PMID 32349206, 2020). "In the limited number of studies where AgRP/NPY or POMC/CART have been measured in mammalian models of stress that result in anorexia, there is some evidence for increased expression of the orexigenic peptide genes but the significance of this finding is uncertain." (PMID 26017156, 2015). "We hypothesized that the activation of NPY/Y1R/AP-1 signaling might be involved in the control of AMPH-induced anorexia." (PMID 24225225, 2013). "Thus, the possibility that the hypothalamic NPY-Y1R-AP1 signals played a role in the control of AMPH-mediated anorexia was considered." (PMID 24225225, 2013). "Interestingly, although NPY was thought to play a major role in anorexia and cachexia based on its central reduction in these conditions, measurements of NPY plasma levels in human control and cancer patients did not reveal differences." (PMID 21637823, 2011). "Similarly to our findings, in different models of acute and chronic inflammation-induced anorexia, increased mRNA expression of NPY and AgRP has been observed in the hypothalamus or ARC." (PMID 20953376, 2010). "In our previous studies, there was up-regulation of CRF in the PVN and NPY in the ARC of stressor-exposed LWS chicks, and we postulated that CRF may override the orexigenic effect of NPY upon exposure to stressors and exacerbate anorexia in the LWS chicks at a later age." (PMID 32349206, 2020). "However, anorexia is unlikely to cause increased mortality in NPY−/− CR mice, as food intake was not different in NPY−/− mice, compared with that in NPY+/+ mice, and all food was completely consumed by both strains." (PMID 28101970, 2017). "NPY is one of the most potent orexigenic peptides, and the rise of its hypothalamic expression in colitis may reflect a counter-regulatory response to the colitis-evoked anorexia." (PMID 25414650, 2014). "This study comprehensively evaluated the changes in blood levels of five gastrointestinal peptide: substance P, neuropeptide (NPY), motilin, ghrelin and leptin, following chemotherapy, and the relationship between these peptides and CINV or anorexia." (PMID 40045433, 2025). "Inflammatory cytokines interfere with hypothalamic appetite control, particularly in the arcuate nucleus: IL-1β and TNF-α reduce neuropeptide Y (NPY) and agouti-related peptide (AgRP), leading to anorexia." (PMID 40927563, 2025). "Both NPY/AgRP and POMC are important downstream targets of insulin, and one of the core roles of insulin is to produce anorexia by suppressing the NPY/AgRP neurons and stimulating POMC neurons." (PMID 33868169, 2021). "The unaltered gene expression of NPY and CART in our models of natural anorexia is actually in line with our original prediction that arcuate nucleus neuropeptide expression would not change because food intake and body weight are at the defended level." (PMID 26017156, 2015). "A study investigated the changes in NPY and GAL peptides at simulated high altitude (HA) and their possible role in anorexia in male SD rats." (PMID 25197671, 2014).
Anorexia (continued). "In the present study, Y1R and AP-1 expression were increased during AMPH treatment and this increase was just opposite to the decrease of NPY, revealing the involvement of NPY-Y1R-AP1 signaling in the regulation of AMPH-induced anorexia." (PMID 24225225, 2013). "Both neuropeptide Y (NPY) and proopiomelanocortin (POMC) are involved in regulating AMPH-induced anorexia." (PMID 24225225, 2013). "Our previous study showed that AgRP, and not neuropeptide Y (NPY) is the principal protein molecule that correlates well with feeding behavior in Japanese seabass from anorexia to adaptation." (PMID 36387900, 2022). "Furthermore, studies should explore the role of CORT in the NHpC, and its roles in mediating NPY and CRF expression during heat stress, as these all seem to be involved in the heat stress response, as well as heat-induced anorexia." (PMID 34827087, 2021). "In this context, it has been shown that CCK and interleukin-1 (IL-1) may synergize to worsen anorexia and that TNF-α may interfere with the orexigenic effect of neuropeptide-Y (NPY)." (PMID 31191339, 2019). "In addition, NPY appears to contribute to insulin resistance induced by acute stimulation of AgRP neurons, and GABA release from AgRP neurons has been shown to inhibit stress-activated, anorexia-inducing neurons located in the parabrachial nucleus." (PMID 40371641, 2025). "In goldfish, intraperitoneal injection of SPX induced anorexia, accompanied by an increase in hypothalamic expression of anorexigenic neuropeptide proopiomelanocortin (POMC), with a simultaneous decrease in orexigenic neuropeptide Y (NPY) and agouti-related peptide (AgRP)." (PMID 35204737, 2022). "In particular, a massive release of cytokines can trigger effects that mimic the leptin hormonal signaling and suppress the ghrelin and neuropeptide Y signaling, without a compensatory response, thus inducing the sustained anorexia frequently observed in cancer patients." (PMID 34055649, 2021). "Importantly, this NPY “peak” was absent in our patients with uremic anorexia, who conversely showed a significant decrease in NPY 90 min after eating that fell below the basal values, explaining the early and late lack of appetite seen in anorexics." (PMID 31191339, 2019). "Some cachectic factors, such as cytokines, can inhibit the neuropeptide Y (NPY) pathway or imitate the negative feedback action of leptin on the hypothalamus, resulting in anorexia." (PMID 26843513, 2016).
diabetes (45 papers, 2009 to 2025). "Previous studies have reported that NPY is associated with the progression of multiple diseases, such as hypertension, diabetes, CH and other cardiovascular diseases 12, 34-36." (PMID 33390770, 2021). "Excess release of NPY can lead to overeating causing excessive energy intake, subsequently precipitating a series of damaging effects resulting in diabetes, heart disease, and other illnesses." (PMID 32831640, 2020). "The investigators compared the food intake patterns of NPY deficient and wild type mice after inducing diabetes with streptozotocin (STZ)." (PMID 25197671, 2014). "The study showed that after 2 weeks of diabetes onset, the food intake of wild mice was increased by 50% when compared to NPY deficient mice." (PMID 25197671, 2014). "Glibenclamide (used to treat type 2 diabetes mellitus) promoted the release of NPY from hamster insulinoma tumor cells, and NPY blocked insulin release in the insulinoma RIN 5AH cell line; the latter action was due to the Y1R/adenylyl cyclase inhibition." (PMID 37373115, 2023). "Down-regulations of both FAIM2 and NPY were been strong negatively correlated with diabetes (R/p value: − 0.484/0.026)." (PMID 36329447, 2022). "Together, these results indicate that dysregulated NPY/Y1 signaling in β cells acts as one of the key drivers to diabetes progression, as evident by the improved β-cell function under blockage of Y1 signaling." (PMID 34890851, 2022). "Reducing plasma neuropeptide Y (NPY) effectively delays the occurrence of diabetes and its complications." (PMID 33954169, 2020). "NPY levels are significantly greater in women, patients with diabetes (especially insulin controlled), and patients with hypertension (especially those taking hydralazine)." (PMID 31876927, 2020). "Collectively, it is suggested that NPY/AgRP neurons are more susceptible to l-lactate than the POMC neurons in the hypothalamic ARC, conditions that can be associated with diabetes-induced alterations in feeding behavior." (PMID 33219201, 2020). "The key to the development of diabetes is insufficient insulin secretion and insulin resistance, and NPY is involved in these processes." (PMID 33123166, 2020). "Present results reveal that STZ-induced diabetes modified the sympathetic nerve endings surrounding the mesenteric artery, reducing the outflow of ir-NPY while increasing ATP and adenosine (ADO) overflow elicited by EFS." (PMID 29896104, 2018). "In particular, sympathetic nerve endings are modified by diabetes altering either the tissue content or the release of sympathetic co-transmitters noradrenaline (NA), neuropeptide tyrosine (NPY), and ATP." (PMID 29896104, 2018). "This study aimed to investigate the alteration of Neuropeptide Y (NPY) in the hypothalamus and its correlation with insulin, leptin and ghrelin during the development of a rat model of type 2 diabetes mellitus." (PMID 27867820, 2016). "In clinical T1DM, a diabetes-related decrease in [NPY] is attributed to impaired sympathetic function, whereas increased [NPY] is attributed to sympathetic overactivity." (PMID 26885531, 2016). "With the development of the type 2 diabetes mellitus model in rats, the expression of hypothalamic NPY mRNA showed a time-dependent increase." (PMID 27867820, 2016). "With the development of the type 2 diabetes mellitus rat model, the hypothalamic NPY content increased in a time-dependent manner in the rats (P < 0.01)." (PMID 27867820, 2016). "Results shown here demonstrate increased expression of NPY mRNA and protein in the diabetes control (DM) group in contrast to the NC group (P < 0.01) which corresponds with the major diabetic symptom of overeating." (PMID 25197671, 2014). "Also, the selective activation of PPARɣ in NPY1R-expressing adipocytes using a molecule that covalently links tesaglitazar to neuropeptide Y was shown to enhance adipocyte differentiation and to prevent diabetes progression in db/db mice." (PMID 35995995, 2022).
diabetes (continued). "In the pancreas, while PYY and PP are expressed by α-cells and pancreatic PP cells, respectively, recent studies have demonstrated that NPY expression in mouse islet β-cells may play a role in altered β-cell function that precedes diabetes onset." (PMID 34890851, 2022). "We therefore sought to determine whether FGF1 inhibits NPY/AgRP neurons and, if so, whether this inhibitory effect is sufficiently durable to offer a feasible explanation for sustained diabetes remission induced by central administration of FGF1." (PMID 35917179, 2022). "Our data exhibit that infusion of MSCs and its combination therapy with insulin might ameliorate diabetes signs by changing the amount of leptin and subsequent changes in the expression of neuropeptide Y and melanocortin-4 receptor." (PMID 32405365, 2020). "As NPY receptors are expressed in the inner retina and recognition that RGC are perturbed in diabetes, we then wished to evaluate whether NPY played a homeostatic role and exerted a protective effect to preserve RGC." (PMID 32141716, 2020). "In conclusion, the present results highlight that within 5–6 weeks of STZ-induced diabetes, sympathetic nerve terminal alterations are relevant and are related to a reduced ir-NPY overflow plus increases in ATP and ADO outflow in the sympathetic nerve endings of the rat arterial mesentery bed." (PMID 29896104, 2018). "High CSF NPY concentrations are related to male gender, diabetes, and low plasma cholesterol." (PMID 30327597, 2018). "During the development of the type 2 diabetes mellitus rat model, the hypothalamic NPY content and NPY mRNA expression increased in a time-dependent manner, which was positively correlated with the changes of the serum insulin and leptin and negatively correlated with the plasma ghrelin." (PMID 27867820, 2016). "During the development of the type 2 diabetes mellitus rat model, both the fasting serum levels of insulin and leptin (ng/ml) elevated significantly and the fasting plasma ghrelin concentration decreased the hypothalamic NPY (pg/mg) content significantly." (PMID 27867820, 2016). "During the development of the type 2 diabetes mellitus rat model, the changes in hypothalamic NPY contents and its correlation with the insulin, leptin, and ghrelin levels, as well as the potential mechanism underlying their interactions have not yet been reported." (PMID 27867820, 2016). "Other authors have suggested that the reduction in food and water intake could be due to the fact that V reduces the increased production of neuropeptide Y (NPY) that occurs in diabetes." (PMID 24511298, 2014). "In addition, STZ-induced diabetes increased the NPY content of both the corpus cavernosum and seminal vesicle." (PMID 24847201, 2014). "In addition to their effects on glucose metabolism, DPP4 inhibitors such as sitagliptin, vildagliptin, linagliptin and saxagliptin also inhibit the degradation of NPY, thereby increasing its blood concentration in healthy individuals and patients with type 2 diabetes mellitus." (PMID 40490517, 2025). "The remarkably long-lived duration of this inhibitory effect is compatible with a role for reduced NPY/AgRP neuron activity in the effect of FGF1 to induce sustained diabetes remission in Lepob/ob mice, although additional studies are needed to test this hypothesis directly." (PMID 35917179, 2022). "However, in diabetic retinas (and seen in the STZ model) more insidious pathophysiological changes are observed, which show reduced NPY (gene and protein) expression in the mouse retina, more relevant to human diabetes, and emphasize the importance of the context and how the results are interpreted." (PMID 32141716, 2020). "NPY expression declines postnatally with β-cell maturation, and its re-emergence in animal models of β-cell dysfunction, for example, in β-cell-specific Neurod1 knockout mice, or during diabetes, is thought to contribute to altered β-cell identity and impaired GSIS." (PMID 30303066, 2018).